AGPAT2 (1-acylglycerol-3-phosphate O-acyltransferase 2)
Description:
Converts 1-acyl-sn-glycerol-3-phosphate (lysophosphatidic acid or LPA) into 1,2-diacyl-sn-glycerol-3-phosphate (phosphatidic acid or PA) by incorporating an acyl moiety at the sn-2 position of the glycerol backbone.
Synonyms: LPAAT-beta; LPLAT2; 1-AGPAT2; BSCL; BSCL1; LPAAB
Tractability: Small molecule: it belongs to a druggable protein family. Antibody: its Gene Ontology location is reachable by antibodies, with high confidence; UniProt predicts a signal peptide or a membrane-spanning region. PROTAC: ubiquitination databases record sites on it; its protein half-life has been measured; a small molecule that binds it is known.
Target class: Enzyme; Transferase
Gene: Protein-coding gene on chromosome 9 (136,673,142 to 136,687,457, reverse strand). Ensembl gene ENSG00000169692.
Subcellular location: Endoplasmic reticulum membrane
Pathways (Reactome):
Gene expression (Transcription): MLL4 and MLL3 complexes regulate expression of PPARG target genes in adipogenesis and hepatic steatosis
Immune System: Neutrophil degranulation
Metabolism: Synthesis of PA
Gene Ontology:
Molecular function: 1-acylglycerol-3-phosphate O-acyltransferase activity; acyltransferase activity
Biological process: phosphatidic acid biosynthetic process; positive regulation of cytokine production; phospholipid metabolic process; positive regulation of cytokine-mediated signaling pathway; CDP-diacylglycerol biosynthetic process; epidermis development; phospholipid biosynthetic process; response to xenobiotic stimulus; triglyceride biosynthetic process
Cellular component: endoplasmic reticulum; endoplasmic reticulum membrane; plasma membrane; specific granule membrane; membrane
Genetic constraint (gnomAD): Loss-of-function variants: 18 observed, 22.27 expected, observed/expected ratio (o/e) 0.81, 90% interval 0.56 to 1.2. The synonymous counts are far from expectation, so gnomAD's model fits this gene poorly and the ratio says little. Missense variants: 415 observed, 369.86 expected, observed/expected ratio (o/e) 1.12, 90% interval 1.03 to 1.22. Synonymous variants: 200 observed, 161.36 expected, observed/expected ratio (o/e) 1.24, 90% interval 1.1 to 1.39.
Gene-disease validity (ClinGen):
ClinGen rates the evidence that AGPAT2 causes each of these diseases.
lipodystrophy (autosomal recessive): Definitive. A congenital or acquired disorder characterized by abnormal loss or redistribution of the adipose tissue in the body.
Homologues: Orthologues: chimpanzee AGPAT2 (98% identical), macaque AGPAT2 (81% identical), pig AGPAT2 (78% identical), mouse Agpat2 (77% identical), dog AGPAT2 (76% identical), guinea pig AGPAT2 (76% identical), rat Agpat2 (71% identical), tropical clawed frog agpat2 (56% identical), zebrafish agpat2 (47% identical), Drosophila melanogaster Agpat1 (33% identical), Caenorhabditis elegans acl-2 (32% identical), Caenorhabditis elegans acl-1 (30% identical), and 1 more. Paralogues in human: AGPAT1 (47% identical).
Diseases named in the same sentence as AGPAT2 in open-access papers:
AGPAT2 is named in the same sentence as 64 diseases in open-access papers, as found by Europe PMC text mining. Sharing a sentence is not in itself a finding about the gene and the disease. The quoted sentences say what the papers report.
lipodystrophy (38 papers, 2009 to 2025). "The difference in host response to infection is more likely to be caused by the metabolic derangement of the lipodystrophy, instead of cell-specific expression and/or isoforms of AGPAT2." (PMID 38755198, 2024). "It was reported that mice with a targeted mutation in the Agpat2 gene developed severe lipodystrophy, affecting both white and brown adipose tissue and causing extreme insulin resistance, diabetes, and hepatic steatosis." (PMID 36837811, 2023). "This strongly suggests that lipodystrophy was the cause of the metabolic disorders described in AGPAT2 KO mice." (PMID 35250856, 2022). "Overall, our study reveals novel mechanistic insights regarding the molecular pathogenesis of severe lipodystrophy caused by mutations in either seipin or AGPAT2." (PMID 32094408, 2020). "Several genetic mutations are strongly associated with lipodystrophy, including mutations in Agpat2, Pparγ, Lmna, Zmpste24, Akt2, and Bscl2." (PMID 28643267, 2018). "Based on our findings, we expect that application of WGS in cases of unexplained lipodystrophy will not only identify novel lipodystrophy-associated loci, but will also reveal more cases of heterozygous AGPAT2 variants." (PMID 30319454, 2018). "Here we report a single complex AGPAT2 allele [V67M;V167A] in an adult female suffering from partial lipodystrophy by whole genome sequencing (WGS)." (PMID 30319454, 2018). "Mutations in 1-acylglycerol-3-phosphate O-acyltransferase 2 (AGPAT2), Berardinelli-Seip congenital lipodystrophy 2/Seipin and caveolin-1 cause congenital complete lipodystrophy." (PMID 25695774, 2015). "The exact mechanisms of lipodystrophy in patients with AGPAT2 mutations remain elusive but possibly involve impaired adipogenesis owing to abnormal lipid signaling." (PMID 24498038, 2014). "What role does altered phospholipid levels play in the pathogenesis of lipodystrophies in patients with AGPAT2 and BSCL2/SEIPIN mutations?" (PMID 23740690, 2013). "Generally, defects in AGPAT2 cause inherited lipodystrophy, a genetic disorder characterized by the selective loss of adipose tissue (fat loss)." (PMID 20017992, 2009). "Of note, AGPAT2 KO adipocytes are devoid of caveolae, a subclass of membrane microdomains involved in adipocyte fat storage and whose deficiency is associated with lipodystrophy (see later)." (PMID 35250856, 2022). "Our results unveil a mechanism by which AGPAT2 deficiency may lead to an increase of cellular PA and cause lipodystrophy." (PMID 34824276, 2021). "Together, these findings suggest that additional genetic or other factors may be required to reduce the activity of the intact AGPAT2 allele below a critical threshold level, resulting in a partial lipodystrophy phenotype." (PMID 30319454, 2018). "Also, AGPAT2 involved in lipodystrophy and defects in CPT2 causes carnitine palmitoyltransferase II deficiency (Orngreen, Ejstrup & Vissing, 2003)." (PMID 27478693, 2016). "It is unclear whether this downregulation is a consequence of lipodystrophy, or perhaps the variant found in AGPAT2, p.X18Leu; rs201504151, which has a frequency of 7% in the population, might contribute to this effect." (PMID 26176221, 2015). "However, the 8th lipodystrophy-associated A239V mutation had only mild effect on AGPAT2 enzyme activity (90% of wild-type), suggesting the involvement of additional factors." (PMID 25195639, 2014). "BSCL2 mutations exhibit more severe lipodystrophy and metabolic alterations than AGPAT2 mutations." (PMID 23740690, 2013). "Interestingly, mice deficient in AGPAT2, the BSCL1 lipodystrophy gene, were recently found to have normal or low levels of serum free fatty acids, but still developed robust liver steatosis." (PMID 21533227, 2011). "Exactly how AGPAT2 deficiency causes lipodystrophy, i.e., BSCL1, is unknown." (PMID 34824276, 2021). "The mechanisms of lipodystrophy in patients with mutation of AGPAT2 gene remain unknown." (PMID 24498038, 2014).
lipodystrophy (continued). "Assays in Agpat2 knockout mice demonstrated the development of severe lipodystrophy affecting both white and brown AT and a metabolic condition characteristic of CGL." (PMID 40508223, 2025). "AGPAT2-/- mice reproduce all the features of human lipodystrophy, including hyperinsulinemia, diabetes, hypertriglyceridemia, and hepatic steatosis." (PMID 36978948, 2023). "Conversely, Lpaatβ/Agpat2 knockout mice are hyperglycemic, reflecting the severe insulin resistance that is manifest in this model of lipodystrophy." (PMID 36362872, 2022). "Lpaatβ/Agpat2 knockout mice also exhibit a more severe metabolic phenotype than Lpaatα/Agpat1 knockout mice, with the development of a generalized lipodystrophy." (PMID 36362872, 2022). "In models of classical lipodystrophy, such as global Agpat2-knockout mice or adipocyte-specific Bscl2-knockout mice, the body weights are usually lower than control littermate despite organomegaly." (PMID 32797353, 2021). "We directly sequenced all exons of genes associated with lipodystrophy including LMNA, ZMPSTE24, AGPAT2, BSCL2, CAV1, PTRF, and PPARγ2." (PMID 31293201, 2019). "Among these mutants, AGPAT2 induced lipodystrophy was indicated either by reducing triglyceride accumulation in adipocytes or levels of glycerophospholipids and hence affecting adipocyte function." (PMID 28643267, 2018). "Identification of additional heterozygous AGPAT2 cases, within the rare group of subtle and partial lipodystrophies, is needed to investigate this further." (PMID 30319454, 2018). "The common duplication of PMP22 was ruled out by clinical-grade testing, and genes known to cause lipodystrophy (LMNA, PPARG, EMD, AGPAT2, BSCL2) were also sequenced." (PMID 28050599, 2017). "Mutations in several genes have been found in patients with inherited lipodystrophies, including mutations in LMNA, PPARG, AKT2 and ZMPSTE24 in partial lipodystrophy, and mutations in AGPAT2, BSCL2, CAV1 and PTRF in congenital total lipodystrophy." (PMID 26987365, 2016). "Indications for this are supported by additional rare variants we found in AGPAT2 and LPIN1 lipodystrophy genes." (PMID 26176221, 2015). "AGPAT2−/− mice developed severe lipodystrophy, which affected both white and brown adipose tissue, extreme insulin resistance, diabetes, and hepatic steatosis." (PMID 25415055, 2014). "Moreover, severe lipodystrophy as well as extreme insulin resistance and hepatic steatosis have been observed in AGPAT2−/− mice." (PMID 34907161, 2021). "The classical clinical presentation of a patient with AGPAT2-associated lipodystrophy shows normal cognition and no development of polyneuropathy." (PMID 30563316, 2019). "Examination of the raw images of CEBPA/AGPAT2 ablated cells revealed cells with decreased lipid accumulation compared to controls, but did not appear distinctive on manual visual inspection in comparison to ablation of other lipodystrophy genes such as PPARG." (PMID 30940487, 2019). "So far, no obvious lipodystrophy (either generalized or partial) phenotypes have been described in individuals with heterozygous AGPAT2 mutations." (PMID 30319454, 2018). "When looking at lipodystrophy genes, AGPAT2 is significantly downregulated." (PMID 26176221, 2015). "AGPAT2 may also have a role in the differentiation of adipocytes and defects in this process may also result in lipodystrophy." (PMID 25415055, 2014). "However, it is puzzling that whereas the two sisters reported here share identical abnormalities in AGPAT2 gene and equivalent level of lipodystrophy, they have notoriously dissimilar severity in their metabolic complications." (PMID 24498038, 2014). "How AGPAT2 and LPIN1 mutations cause lipodystrophy is uncertain." (PMID 23740690, 2013). "Therefore, it is likely that three known lipodystrophy genes (AGPAT2, Lipin and Seipin) are all involved in PA metabolism." (PMID 21533227, 2011).
lipodystrophy (continued). "A recent study demonstrated decreased Agpat2 levels in white adipose tissue (WAT) of adult mice, resulting in lipodystrophy and inflammation in both WAT and the liver." (PMID 40508223, 2025). "For two lipodystrophy genes, BSCL2 and AGPAT2, sub-clusters with PLIN1 and CEBPA identifed by morphological similarity were validated by independent experiments as novel protein–protein and gene regulatory interactions." (PMID 30940487, 2019). "Metreleptin use is associated with the lowering of triglycerides and haemoglobin A1c (HbA1c) in all lipodystrophy (n = 111), partial (n = 71) and generalised lipodystrophy (n = 41), and in LMNA, PPARG, AGPAT2 or BSCL2 subgroups (n = 72,13,21 and 21 respectively)." (PMID 37794082, 2023). "BMI was lower after treatment in aggregated lipodystrophy, in generalized and partial subgroups, and in those with LMNA or BSCL2 mutations, but not PPARG or AGPAT2 mutations (Level 3 evidence)." (PMID 37794082, 2023). "In contrast to AGPAT2, LPIN1 mutations have been found to be associated with lipodystrophy only in mouse models; there are no known human LPIN1 mutations causing lipodystrophy." (PMID 23740690, 2013). "Lipodystrophy related genes were also induced in WAT of eNOS ko animals (Lipin1, Agpat2)." (PMID 21781316, 2011). "The patient was found to carry no mutation in any of the known lipodystrophy-causing genes (LMNA, PPARG, BSCL, AGPAT2, LMNB2, CAV1) by exon-by-exon sequence analysis." (PMID 19830242, 2009).
generalized lipodystrophy (23 papers, 2012 to 2025). Almost complete absence of subcutaneous and/or visceral adipose tissue. "Individuals reported in the studies included 90 with partial lipodystrophy (72 due to LMNA mutation and 15 due to PPARG mutation), 42 with generalized lipodystrophy (21 AGPAT2, 21 BSCL2, 2 LMNA), and 19 with IR due to INSR mutation(s)." (PMID 37794082, 2023). "AGPAT2 is the only AGPAT isoform whose loss-of-function mutations cause a severe form of human congenital generalized lipodystrophy." (PMID 34824276, 2021). "Thirty-seven different mutations in AGPAT2 have been described worldwide related to congenital generalized lipodystrophy." (PMID 32280377, 2020). "It has been reported that inactivating the mutation of AGPAT2 causes congenital generalized lipodystrophy." (PMID 30813330, 2019). "So far homozygous and compound heterozygous mutations in AGPAT2 have only been associated with generalized lipodystrophy." (PMID 30319454, 2018). "Mutations in the gene associated with glycerolipid synthesis, such as AGPAT2 (1-acylglycerol-3-phosphate O-acyltransferase 2, also known as BSCL1), are associated with congenital generalized lipodystrophy, or Berardinelli-Seip syndrome." (PMID 28986436, 2017). "Disruption of the genes encoding either seipin or 1-acylglycerol-3-phosphate O-acyltransferase 2 (AGPAT2) causes severe congenital generalized lipodystrophy (CGL) in humans." (PMID 25737955, 2015). "The main known candidate genes associated with congenital generalized lipodystrophy, i.e. BSCL1/AGPAT2, BSCL2/seipin, BSCL3/caveolin-1 and BSCL4/PRTF were analyzed." (PMID 23919306, 2013). "In this study, we investigated clinical features of the first families with congenital generalized lipodystrophy in Persian population and identified the disease causing AGPAT2 mutations in these two unrelated cases." (PMID 22902344, 2012). "However, the absence of autoimmune markers, the presence of lifelong fat loss since infancy, and compound heterozygous AGPAT2 mutations confirmed the diagnosis of congenital generalized lipodystrophy." (PMID 41341138, 2025). "Molecular analysis of the AGPAT2 gene, including sequencing of all six coding exons and the intron–exon boundaries by direct sequencing, revealed pathogenic variants associated with congenital generalized lipodystrophy." (PMID 41341138, 2025). "AGPATs play crucial roles in lipid homeostasis, because enzyme-inactivating mutations in AGPAT2 are linked to congenital generalized lipodystrophy and defects in PA metabolism as well as autophagy are associated with neurological disorders and chronic obstructive pulmonary disease." (PMID 34907161, 2021). "Mutations in AGPAT2 may cause congenital generalized lipodystrophy by inhibiting triacylglycerol synthesis and storage in adipocytes." (PMID 26176221, 2015). "Homozygous disruption of either BSCL2 or AGPAT2, encoding seipin and 1-acylglycerol-3-phosphate O-acyltransferase 2 (AGPAT2) respectively, causes a very severe congenital generalized lipodystrophy (CGL)." (PMID 25737955, 2015). "The critical roles of AGPAT2 in the synthesis of TAG in human adipocytes were established from studies on patients with mutations in the AGPAT2 gene, which causes congenital generalized lipodystrophy (CGL)." (PMID 25415055, 2014). "Two major forms of congenital generalized lipodystrophy, CGL1 (caused by AGPAT2 mutations) and CGL2 (due to mutation in BSCL2), account for 95% of all cases." (PMID 22902344, 2012). "A large number of studies show that congenital generalized lipodystrophy is caused by a lack of the AGPAT2 gene, indicating that the AGPAT2 gene is closely related to fat metabolism." (PMID 35073667, 2023). "In the case of genes causing generalized lipodystrophy, this may reflect the fact that while disruption of BSCL2 or AGPAT2 leads principally to a lack of adipose tissue, PTRF and CAV1 mutations cause a more complex phenotype in affected patients." (PMID 30940487, 2019).
Insulin resistance (15 papers, 2013 to 2025). Increased resistance towards insulin, that is, diminished effectiveness of insulin in reducing blood glucose levels. "Both women had CGL1 due to AGPAT2 mutations and presented with profound hypoleptinemia, amenorrhea, and severe insulin resistance." (PMID 41341138, 2025). "Another study demonstrated that liver fat accumulation in Agpat2 knockout mice resulted from AT loss and insulin resistance." (PMID 40508223, 2025). "Several are the metabolic complications related to AGPAT2 functional loss, insulin resistance is a hallmark of the disease and usually progresses during childhood leading to diabetes mellitus after adolescence." (PMID 32117065, 2020). "Additionally, emerging research has also linked AGPAT2 to different pathological conditions, such as obesity, insulin resistance, and cancer." (PMID 40508223, 2025). "Additionally, severe insulin resistance is found in generalized and partial lipodystrophy syndromes associated with pathogenic variants in AGPAT2, LMNA, and PPARG." (PMID 33210059, 2020). "AGPAT2 mutation can lead to congenital systemic adipotrophic diabetes (GCL), which is characterized by adipose tissue deficiency, insulin resistance, diabetes, and hyperlipidemia." (PMID 32184719, 2020). "Elevated blood glucose is indicative of an increased metabolic burden in the liver, suggesting that AGPAT2 knock-down may lead to severe insulin resistance in Nile tilapia, similar to that observed in AGPAT2(−/−) mice." (PMID 36978948, 2023). "AGPAT2 KO mice develop a phenotype resembling that of BSCL type 1 (BSCL1) in humans characterized by near total loss of white and brown adipose tissue with severe insulin resistance, diabetes, and hepatic steatosis." (PMID 32117065, 2020). "Numerous genes are candidates for severe insulin resistance, such as INSR, BSCL2, AGPAT2, CAV1, and PTRF." (PMID 33995269, 2021).
diabetes (11 papers, 2013 to 2024). "The fifth family had two children diagnosed and treated with leptin in the diabetes clinic and were confirmed to be homozygous for a mutation in AGPAT2 c.158del, causing a change in the protein p.(Gly53Alafs*8), NM_006412.4." (PMID 38231342, 2024). "We report CGL1 in two Saudi female siblings with lipoatrophy, diabetes mellitus, hypertriglyceridemia, steatohepatitis, and acanthosis due to very rare homozygous 1-acylglycerol-3-phosphate O-acyltransferase β (AGPAT2) genetic variant." (PMID 35474974, 2022). "In summary, patients with BSCL2 mutations show earlier age of onset of diabetes mellitus, higher risk to suffer from premature death and mental retardation and are more severe than patients with AGPAT2 mutations." (PMID 32349771, 2020). "We screened the AGPAT2 gene in two siblings who presented with pseudoacromegaly,diabetes and severe dyslipidaemia and identified a novel mutation in AGPAT2 causing a single amino acid substitution,p.Cys48Arg." (PMID 23430550, 2013). "While AGPAT2 is known to be associated with Berardinelli–Seip congenital lipodystrophy (BSCL) syndrome, it is characterized by the absence of fat predisposition to develop diabetes mellitus, and further correlates with mutational spectrum forming phenotypic heterogeneity." (PMID 29986445, 2018).